AHR (aryl hydrocarbon receptor)
Description:
Ligand-activated transcription factor that enables cells to adapt to changing conditions by sensing compounds from the environment, diet, microbiome and cellular metabolism, and which plays important roles in development, immunity and cancer. Upon ligand binding, translocates into the nucleus, where it heterodimerizes with ARNT and induces transcription by binding to xenobiotic response elements (XRE). Regulates a variety of biological processes, including angiogenesis, hematopoiesis, drug and lipid metabolism, cell motility and immune modulation. Xenobiotics can act as ligands: upon xenobiotic-binding, activates the expression of multiple phase I and II xenobiotic chemical metabolizing enzyme genes (such as the CYP1A1 gene). Mediates biochemical and toxic effects of halogenated aromatic hydrocarbons. Next to xenobiotics, natural ligands derived from plants, microbiota, and endogenous metabolism are potent AHR agonists. Tryptophan (Trp) derivatives constitute an important class of endogenous AHR ligands. Acts as a negative regulator of anti-tumor immunity: indoles and kynurenic acid generated by Trp catabolism act as ligand and activate AHR, thereby promoting AHR-driven cancer cell motility and suppressing adaptive immunity. Regulates the circadian clock by inhibiting the basal and circadian expression of the core circadian component PER1. Inhibits PER1 by repressing the CLOCK-BMAL1 heterodimer mediated transcriptional activation of PER1. The heterodimer ARNT:AHR binds to the dioxin response element (DRE) of target gene promoters and activates their transcription.
Synonyms: bHLHe76; FVH3; RP85
Tractability: Small molecule: an approved drug acts on it; a structure with a bound ligand is known; a high-quality ligand is known; it belongs to a druggable protein family. PROTAC: it is named in the literature on targeted protein degradation; ubiquitination databases record sites on it; its protein half-life has been measured; a small molecule that binds it is known.
Target class: Transcription factor
Safety:
Unwanted effects reported when the protein is acted on. In parentheses: how it was acted on, where the effect was seen, and who reports it.
Accumulation, Liver lipid (activation; source: AOP-Wiki)
Formation, Hepatocellular and Bile duct tumors (activation; source: AOP-Wiki)
Increase, Early Life Stage Mortality (activation; source: AOP-Wiki)
N/A, Breast Cancer (activation; source: AOP-Wiki)
Uroporphyria (activation; source: AOP-Wiki)
Gene: Protein-coding gene on chromosome 7 (16,916,359 to 17,346,152, forward strand). Ensembl gene ENSG00000106546.
Subcellular location: Cytoplasm; Nucleus
Subcellular location (Human Protein Atlas): Cytosol; Nucleoplasm
Pathways (Reactome):
Metabolism: Aryl hydrocarbon receptor signalling; Endogenous sterols; PPARA activates gene expression; Phase I - Functionalization of compounds; Xenobiotics
Gene Ontology:
Molecular function: cis-regulatory region sequence-specific DNA binding; DNA binding; DNA-binding transcription factor activity; Hsp90 protein binding; nuclear receptor activity; protein binding; protein heterodimerization activity; RNA polymerase II-specific DNA-binding transcription factor binding; sequence-specific double-stranded DNA binding; TBP-class protein binding; TFIID-class transcription factor complex binding; transcription cis-regulatory region binding; transcription coactivator binding; DNA-binding transcription factor activity, RNA polymerase II-specific; E-box binding; protein homodimerization activity; protein dimerization activity
Biological process: cellular response to 2,3,7,8-tetrachlorodibenzodioxine; cellular response to cAMP; cellular response to forskolin; cellular response to molecule of bacterial origin; negative regulation of inflammatory response; negative regulation of T cell mediated immune response to tumor cell; positive regulation of transcription by RNA polymerase II; regulation of adaptive immune response; regulation of B cell proliferation; regulation of DNA-templated transcription; regulation of gene expression; regulation of transcription by RNA polymerase II; response to toxic substance; response to xenobiotic stimulus; apoptotic process; blood vessel development; circadian regulation of gene expression; negative regulation of DNA-templated transcription; positive regulation of DNA-templated transcription; xenobiotic metabolic process; intracellular receptor signaling pathway; regulation of multicellular organismal process
Cellular component: cytoplasm; cytosol; nuclear aryl hydrocarbon receptor complex; nucleoplasm; nucleus; protein-containing complex; aryl hydrocarbon receptor complex; chromatin; cytosolic aryl hydrocarbon receptor complex; transcription regulator complex
Genetic constraint (gnomAD): Loss-of-function variants: 33 observed, 72.86 expected, observed/expected ratio (o/e) 0.45, 90% interval 0.34 to 0.61. The upper end of that interval is the gene's LOEUF score, 0.61, which puts it in group 2 of 6, group 1 being the genes least tolerant of losing a copy. Missense variants: 918 observed, 974.7 expected, observed/expected ratio (o/e) 0.94, 90% interval 0.89 to 1. Synonymous variants: 357 observed, 339.68 expected, observed/expected ratio (o/e) 1.05, 90% interval 0.96 to 1.15.
Homologues: Orthologues: chimpanzee AHR (99% identical), macaque AHR (95% identical), dog AHR (85% identical), pig AHR (82% identical), rabbit AHR (77% identical), guinea pig AHR (75% identical), mouse Ahr (69% identical), rat Ahr (69% identical), tropical clawed frog ahr (57% identical), zebrafish ahr1a (39% identical), Drosophila melanogaster ss (29% identical), Caenorhabditis elegans ahr-1 (22% identical). Paralogues in human: AHRR (24% identical).
Diseases named in the same sentence as AHR in open-access papers:
AHR is named in the same sentence as 575 diseases in open-access papers, as found by Europe PMC text mining. Sharing a sentence is not in itself a finding about the gene and the disease. The quoted sentences say what the papers report.
colitis (314 papers, 2011 to 2026). Inflammation of the colon. "For example, the deletion of the IBD susceptibility gene CARD9 alters the gut microbiota, leading to a reduction in AHR ligand-producing bacteria (such as Lactobacillus reuteri), thereby weakening AHR signaling and increasing susceptibility to colitis." (PMID 41602107, 2026). "AhR is constitutively expressed in intestinal epithelial cell (IEC) and immune cells, and its expression is reduced in intestinal tissue from IBD patients; moreover, AhR deficiency disrupts intestinal immunity and exacerbates colitis." (PMID 41530817, 2026). "Collectively, our findings demonstrated that AhR‐mediated induction of BD1 plays a crucial role in reversing colitis‐associated dysbiosis." (PMID 40410944, 2025). "Activation of the aryl hydrocarbon receptor (AHR) by spermidine, a naturally occurring polyamine found in food, reportedly alleviated the intestinal barrier dysfunction associated with colitis." (PMID 40722954, 2025). "Taken together, these findings reveal a new function for activating AhR in upregulating BD‐1, thereby expanding our knowledge of the pathophysiology of human colitis caused by a compromised AhR pathway." (PMID 40410944, 2025). "Like pretreatment, post‐treatment of colitis mice with I3C suppressed colitis and colitis associated symptoms and increased the expression of AhR and BD1 at both mRNA and protein levels." (PMID 40410944, 2025). "We analyzed the colitis associated symptoms and mRNA and protein expression of AhR and BD1 in CECs from control and experimental animals." (PMID 40410944, 2025). "AHR-null mice exhibit enhanced susceptibility to colitis and Citrobacter rodentium infection due to a reduction of ILC3s-derived IL-22 production in the intestine." (PMID 41194916, 2025). "AhR activation has been linked to the alleviation of colitis by reducing inflammatory cytokines like IL‐1β, IL‐6, and TNF‐α, while enhancing anti‐inflammatory cytokines, such as IL‐4, IL‐10, and IL‐22, and strengthening the intestinal epithelial barrier." (PMID 39836604, 2025). "Our findings demonstrated for the first time the direct transcriptional upregulation of BD‐1 following AhR activation, and consequently reversal of the colitis‐associated dysbiosis in the gut microbiota and colonic inflammation." (PMID 40410944, 2025). "This strongly suggests regulation of colitis-associated Bacteroides in female mice was dependent on AhR expression in Rorc-expressing." (PMID 39229279, 2024). "Collectively, these results indicate that AhR deficiency exacerbated DSS-induced colitis and LPS-induced inflammation, suggesting a protective role for AhR in controlling inflammatory responses and immune homeostasis." (PMID 39113799, 2024). "In the current study, we discovered that, in a colitis mouse model, AhR deficiency mediated dynamic remodeling of the cellular composition of intestinal lamina propria (LP) CD45+ immune cells, with a significant increase in the monocyte-macrophage lineage." (PMID 39113799, 2024). "In summary, we utilized AHR knockout mice to demonstrate that LA alleviated the colitis aggravation and Th17/Treg cell imbalance caused by Pg in an AHR-dependent manner in vivo." (PMID 38388542, 2024). "Relative to DSS-treated littermate controls, DSS-treated AhR-/- mice showed more severe colitis, characterized by greater body weight loss, higher disease activity index (DAI) score, and shorter colon length." (PMID 39113799, 2024). "At a functional level, the AhR loss in DCs resulted in a more aggressive experimentally-induced colitis, showing that AhR signaling played a role in the regulation of a functional intestinal epithelial barrier and mucosal immunity." (PMID 39211042, 2024). "Mice with AhR deficiency in myeloid cells developed more severe dextran sulfate sodium induced colitis, with concomitant increased macrophage pyroptosis." (PMID 39113799, 2024).
colitis (continued). "ELNs of edible mulberry bark have been shown to reduce cellular damage associated with colitis by promoting the activation of the heat shock protein family A member 8 (HSPA8)-mediated anti-microbial peptides (AhR) signaling pathway." (PMID 38542448, 2024). "Consistently, whole body AhR deletion enhances colitis-associated colorectal tumorigenesis, and supplementation of I3C reduces the number of colorectal tumors in WT, but not in AhR-null mice." (PMID 38518996, 2024). "This deficiency leads to impaired AhR-mediated IL-22 production, rendering them susceptible to colitis." (PMID 38443988, 2024). "Recent evidence indicates intestinal-specific deletion of the AhR promotes carcinogen-induced and colitis-associated colon tumorigenesis." (PMID 38518996, 2024). "AHR-deficient mice show increased susceptibility to colitis and Citrobacter rodentium infection due to impaired ILC3s and low IL-22 in the intestine and the decreased number of intraepithelial lymphocytes." (PMID 37304260, 2023). "In mice, deficiency of AhR in the IECs exacerbated inflammation in the DSS colitis model, but deletion of AhR in the T cells attenuated colitis and was manifested by the infiltration of Th17 cells into the lamina propria." (PMID 37191444, 2023). "Here, we used a DSS-induced colitis model to investigate the effect of loss of AHR’s DNA-binding activity on DSS-induced intestinal inflammation." (PMID 36519841, 2023). "Our findings provide the first evidence that DNA-binding deficient AHR increases intestinal inflammation in the DSS model of colitis." (PMID 36519841, 2023). "After DSS gavage, both WT mice, which feed on a vegetable-free diet, and AHR-deficient mice displayed an increased abundance of Bacteroides and severe colitis." (PMID 37942478, 2023). "Loss of AHR expression or reduced endogenous AHR ligand levels in mice increases their susceptibility to DSS-induced colitis or Citrobacter rodentium infection by dampening inflammatory responses." (PMID 36519841, 2023). "In the same colitis mouse model, AHR ablation leads to susceptibility to bacterial infection due to disruption of tight junction." (PMID 36678175, 2023). "The blockade of the kyn–AhR axis can ameliorate colitis-associated colon cancer through inhibiting the immune tolerance." (PMID 35892593, 2022). "Accordingly, AHR-deficient mice exhibit enhanced susceptibility to severe colitis and Citrobacter rodentium infection." (PMID 35572636, 2022). "Loss of AHR or diets devoid of AHR ligands increase the susceptibility to acute intestinal inflammation in models of colitis." (PMID 35055106, 2022). "Card9-/- mice, which are more susceptible to colitis, have a reduced ability to activate AhR, which is associated with decreased indole acetic acid levels." (PMID 35237276, 2022). "Previously, it was shown that overexpression of CYP1A1 in gut epithelial cells led to decreased AhR ligands (quasi AhR-deficient) and displayed enhanced susceptibility to Citrobacter rodentium-induced colitis." (PMID 36159798, 2022). "Under inflammatory conditions, including CRC, there can be either partial or complete loss of AhR, whereas xenobiotic induced AhR activation has shown to reduce colitis in experimental models." (PMID 33916690, 2021). "AhR deficiency increased the severity of T cell or sodium dextran sulfate (SDS) induced experimental colitis in mice." (PMID 32635461, 2020). "Although AHR signaling has long been recognized to be implicated in the pathogenesis of autoimmune disorders, such as rheumatoid arthritis (RA), colitis, and systemic lupus erythematosus (SLE), its effect on T1D pathogenesis remains less understood." (PMID 32849515, 2020). "Administration of an AHR agonist can rescue the susceptibility of Card9−/−→germ free mice to colitis." (PMID 31696662, 2020).
colitis (continued). "Taken together, these data confirm that dietary AhR ligands ameliorate susceptibility to colitis and show that IL-22, which is critical for barrier homeostasis and also represents an AhR target, inversely correlates with colitis severity." (PMID 32366032, 2020). "AHR-deficient mice exhibit increased vulnerability to colitis and intestinal C. rodentium infection, which is mainly due to the impaired accumulation of ILC3s and IL-22 production in the gut and a decrease in numbers of intraepithelial lymphocytes (IELs)." (PMID 33193381, 2020). "These are ligands for the aryl hydrocarbon receptor (AhR), which activates IL-22 and IL-10 production and is negatively associated with colitis." (PMID 33424846, 2020). "AhR-deficient mice are highly susceptible to dextran sodium sulfate (DSS)-induced colitis, which at least in part results from a reduction of intraepithelial lymphocytes (IELs) and impaired homeostasis of intestinal epithelial cells (IEL)." (PMID 32366032, 2020). "In animal studies, AhR−/− mice were more susceptible to colitis induced by DSS than wild-type (WT) mice." (PMID 33082710, 2020). "The enhanced susceptibility to DSS-induced colitis was reversed by administering an AhR agonist to CARD9−/−FMT → GF mice." (PMID 32133003, 2020). "By other groups and in line with the high susceptibility of AhR−/− mice to development of colitis, we also demonstrated an impaired barrier integrity, low IL-22 levels, and increased colitis susceptibility in mice fed LRD." (PMID 32366032, 2020). "Like the AHR-deficient mice, animals fed purified, phytochemical-free diets exhibit enhanced susceptibility to severe colitis." (PMID 32784381, 2020). "As expected AhR−/− mice were more susceptible to TNBS-induced colitis model as evident from rapid loss of body weight." (PMID 30626868, 2019). "In dextran sodium sulfate- (DSS-) induced colitis, a deficiency in AhR in mouse intestinal epithelial cells exacerbates inflammation." (PMID 31772949, 2019). "The therapeutic effect of NPD-0414-2 and NPD-0414-24 on the ongoing colitis was abrogated in AhR-deficient mice." (PMID 31031628, 2019). "Innate expression of AhR plays a protective role in T-cell-mediated experimental colitis by suppressing pathogenic Th17 cells." (PMID 31772949, 2019). "Aryl hydrocarbon receptor, which has been implicated in sensing colitis‐inducing oxazoles, is upregulated in PP‐NKT cells." (PMID 31304630, 2019). "Mice deficient in CARD-9 display increased susceptibility to colitis due to a loss of bacterial species capable of metabolizing tryptophan into AHR agonists." (PMID 29706647, 2018). "In mice, transfer of AhR-deficient Th cells in a RAG model of colitis induced more severe disease as compared to mice that received WT Th cells." (PMID 29910812, 2018). "On the other hand, when assessing its role in a gut-associated inflammatory response, AhRR deficiency aggravated symptoms of colitis similar to deficiency of the AhR itself." (PMID 27184933, 2016). "Taken together, AhRR-deficiency was found to cause enhanced susceptibility to DSS colitis similar to AhR-deficiency." (PMID 27184933, 2016). "At a functional level, the loss of AhR in APCs resulted in a dysfunctional epithelial barrier, associated with a more aggressive chemically induced colitis compared to wild type animals." (PMID 27068235, 2016). "AhR-deficient mice exhibit shifts in microbial composition (increased Bacteroidetes), marked by increased epithelial permeability and colitis severity, whereas diets enriched in AhR ligands partially reversed these effects." (PMID 27531998, 2016). "Blockade of IL-22 with a neutralizing antibody reversed the therapeutic effect of Ficz in mice with TNBS-colitis, thus indicating that induction of IL-22 is one of the major mechanisms by which AhR signals control pathogenic responses in the gut." (PMID 22082127, 2011).